RNF122 (ring finger protein 122)
Description:
May induce necrosis and apoptosis. May play a role in cell viability.
Synonyms: FLJ12526
Tractability: Antibody: UniProt predicts a signal peptide or a membrane-spanning region. PROTAC: ubiquitination databases record sites on it.
Gene: Protein-coding gene on chromosome 8 (33,547,754 to 33,567,170, reverse strand). Ensembl gene ENSG00000133874.
Subcellular location: Golgi apparatus; Endoplasmic reticulum; Membrane
Gene Ontology:
Molecular function: protein binding; ubiquitin protein ligase activity; ubiquitin-protein transferase activity
Biological process: negative regulation of mitochondrial membrane potential; positive regulation of apoptotic process; proteasome-mediated ubiquitin-dependent protein catabolic process; protein autoubiquitination
Cellular component: cytoplasm; endoplasmic reticulum; Golgi apparatus; membrane
Genetic constraint (gnomAD): Loss-of-function variants: 12 observed, 20.06 expected, observed/expected ratio (o/e) 0.6, 90% interval 0.38 to 0.97. The upper end of that interval is the gene's LOEUF score, 0.97, which puts it in group 4 of 6, group 1 being the genes least tolerant of losing a copy. Missense variants: 143 observed, 165.8 expected, observed/expected ratio (o/e) 0.86, 90% interval 0.75 to 0.99. Synonymous variants: 54 observed, 61.86 expected, observed/expected ratio (o/e) 0.87, 90% interval 0.7 to 1.1.
Homologues: Orthologues: chimpanzee RNF122 (100% identical), dog RNF122 (99% identical), macaque RNF122 (99% identical), pig RNF122 (99% identical), mouse Rnf122 (97% identical), rat Rnf122 (92% identical), guinea pig RNF122 (90% identical), zebrafish rnf122 (83% identical), Caenorhabditis elegans C09E7.7 (25% identical), Caenorhabditis elegans C09E7.8 (23% identical), Caenorhabditis elegans F19B10.10 (23% identical), Caenorhabditis elegans T22B2.1 (23% identical), and 3 more. Paralogues in human: RNF24 (52% identical).
Diseases named in the same sentence as RNF122 in open-access papers:
RNF122 is named in the same sentence as 8 diseases in open-access papers, as found by Europe PMC text mining. Sharing a sentence is not in itself a finding about the gene and the disease. The quoted sentences say what the papers report.
viral infection (4 papers, 2020 to 2025). "MEX3C, TRIM4 and TRIM25 are the most important E3 ligases for positive regulation of RIG-I activity in response to viral infection, whereas RNF122 and RNF125 have been described to mediate the ubiquitin-dependent degradation of this cytosolic innate immune receptor." (PMID 32019099, 2020). "For example, RNF5, RNF122, and RNF215 have been shown to negatively regulate NF-κB-, RIG-I-, or STING-mediated IFN responses during viral infection." (PMID 40261845, 2025).
anaplastic thyroid cancer (1 paper, 2010). "RNF122 is a recently discovered RING finger protein that is associated with HEK293T cell viability and is overexpressed in anaplastic thyroid cancer cells." (PMID 20553626, 2010). "Given the importance of the biological functions of the RING finger proteins and the overexpression of RNF122 in anaplastic thyroid cancer cells, a functional characterization of this gene is highly warranted." (PMID 20553626, 2010). "Comparative genomic hybridization (CGH) has revealed that RNF122 is overexpressed in anaplastic thyroid cancer cells." (PMID 20553626, 2010).
glioma (1 paper, 2024). A benign or malignant brain and spinal cord tumor that arises from glial cells (astrocytes, oligodendrocytes, ependymal cells). "Herein, RNF122 was overexpressed in glioma, and the RNF122 overexpression was discovered to be associated with a poor outcome and may serve as an autonomous prognostic indicator for glioma." (PMID 39218810, 2024). "Furthermore, the examined association between RNF122 mRNA levels and clinicopathological characteristics in 112 glioma patients revealed that the RNF122 mRNA expression level had a significant correlation to the tumor size (p < 0.001), KPS (p < 0.001), and WHO stage (p < 0.001)." (PMID 39218810, 2024). "The first step was to measure RNF122 protein in Normal HA and five glioma cell lines (U‐251, T98G, LN‐229, A‐172, and U‐87MG) by WB." (PMID 39218810, 2024). "WB and qRT‐PCR analysis revealed that RNF122 was significantly overexpressed in glioma and increased with tumor grade compared to NBT, especially in HGG." (PMID 39218810, 2024). "Nevertheless, the involvement of RNF122, particularly in glioma, remains unreported in the literature." (PMID 39218810, 2024). "Data analysis from the TCGA tumor database also demonstrated that RNF122 was overexpressed in gliomas and inversely related to patient outcomes." (PMID 39218810, 2024). "Although RNF122 dysregulation and its biological role in several disorders have been reported before, its possible role in glioma remains unreported." (PMID 39218810, 2024). "According to the results, RNF122 protein levels are greater in glioma cell lines than in HA." (PMID 39218810, 2024). "Herein, the RNF122 clinical relevance as a prognostic marker, as well as its biological role in glioma, was reported, revealing that the overexpressed RNF122 in human glioma tissue and cell lines improved growth of glioma cells, showing that RNF122 is involved in glioma." (PMID 39218810, 2024). "Nevertheless, in glioma, neither the function nor the mechanism of RNF122 was clarified." (PMID 39218810, 2024). "Based on univariate and multivariate Cox regression analyses, RNF122 mRNA expression level was correlated to WHO stage; hence, it was found to be an independent predictor of unfavorable survival outcomes in glioma patients, indicating that RNF122 might be a potential glioma biomarker." (PMID 39218810, 2024).
infection (2 papers, 2021 to 2022). The state of being infected such as from the introduction of a foreign agent such as serum, vaccine, antigenic substance or organism. "Accordingly, mice lacking Rnf122 were less susceptible to infection with VSV, resulting from increased levels of type I IFNs in the serum." (PMID 33808506, 2021). "RNF122 expression is induced upon RNA virus infection and it was shown to interact with RIG-I both under basal conditions and upon infection with VSV." (PMID 33808506, 2021).
tumor (2 papers, 2010 to 2024). "RNF122 promoted tumor cell growth based on the loss/gain of function." (PMID 39218810, 2024). "Performing Ki‐67 IF staining to assess the proliferative tumor index showed that proliferation in the RNF122 knockdown cohorts was reduced more than in the normal cohorts." (PMID 39218810, 2024). "Collectively, JAK2/STAT3/c‐Myc signaling axis activation by RNF122 was indicated to enhance tumor growth." (PMID 39218810, 2024). "Viral vectors are used to directly interfere with the expression of RNF122, reducing its level in tumor cells and thus inhibiting tumor growth." (PMID 39218810, 2024). "RNF122 is expressed in several normal tissues and in tumor tissues and cell lines; RNF122 has been localized to the endoplasmic reticulum (ER) and the Golgi apparatus." (PMID 20553626, 2010). "Collectively, RNF122 enhances tumor development through JAK2/STAT3/c‐Myc signaling axis activation." (PMID 39218810, 2024). "Additionally, performing RNF122 knocking down and overexpressing in LN‐229 and A‐172 cells, respectively, for validating the RNF122 ability to promote tumor growth further through JAK/STAT pathway activation." (PMID 39218810, 2024). "Mechanistically, RNF122 may enhance tumor progression through JAK2/STAT3/c‐Myc signaling pathway activation." (PMID 39218810, 2024). "For example, in GBM, RNF122 may affect PI3K/Akt, MAPK, or other pathways associated with tumor proliferation and survival." (PMID 39218810, 2024). "In addition, we employed qRT‐PCR to assess the RNF122, JAK2, and STAT3 expression levels in tumor samples and performed correlation analysis." (PMID 39218810, 2024).
cancer (1 paper, 2024). A tumor composed of atypical neoplastic, often pleomorphic cells that invade other tissues. "Based on the Cignal finder cancer 10‐pathway reporter array used for screening the potentially involved signaling pathways in this process, the JAK/STAT signaling axis was significantly suppressed by RNF122 knocking down in LN‐229 and A‐172 cells, in contrast to the other signaling axis." (PMID 39218810, 2024).
RNF122 also shares sentences with these, for which no sentence is quoted: attention deficit-hyperactivity disorder (2 papers); glioblastoma (1).